CCL2 (C-C motif chemokine ligand 2)
Diseases named in the same sentence as CCL2 in open-access papers (continued):
Sharing a sentence is not in itself a finding about the gene and the disease.
tumor (continued). "As an inhibitory chemokine, CCL2 blocked T cell tracking into the tumor by binding to CCR2 on T cell surface." (PMID 39544364, 2024). "Monocytes respond strongly to CCL2, the chemoattractant which is produced by tumor cells and attracts monocytes to the tumor locations." (PMID 38349050, 2024). "This axis involves CCL2, predominantly produced by peripheral blood mononuclear cells and tumor cells, and CCR2, mainly expressed in monocytes and macrophages." (PMID 39201480, 2024). "TPV/eGFP-treated subjects demonstrated a marginal regression in tumor volume compared to vehicle controls, again supporting the role CCL-2 and IL-2 play in the negative regulation of BxPC-3 human PDAC xenografts in our immunocompromised test system." (PMID 39200298, 2024). "In gastric cancer, a high level of TG2 activity enhanced inflammation and tumor growth by recruiting macrophages to the tumor via the IL-1β-mediated induction of CCL2 and CXCL10." (PMID 38474044, 2024). "Treatment of murine cancer models with inhibitory CCL2 antibodies controlled tumor progression; however, once treatment was discontinued, the survival rate of mice declined, highlighting the potential of drugs targeting CCL2 in the treatment of solid tumors." (PMID 39350256, 2024). "One possible tumorigenic mechanism of monocyte/macrophages recruited by CCL2 was tumor vascularization." (PMID 38786066, 2024). "CC chemokine ligand‐2 (CCL2) has been found to not only elicit the insensitivity of tumor cells to chemotherapy and hormone therapy but also induce the resistance of tumor cells toward immunotherapy and targeted drugs such as sorafenib." (PMID 39183447, 2024). "Tumor cells can stimulate IL-17 secretion by monocytes through the expression of C-C motif ligand 2 (CCL2), and further promote inflammation and tumor growth." (PMID 39534095, 2024). "Similar effects were noted with the transgenic expression of CCR2b, the receptor for the myeloid attractant CCL2, in a variety of tumor models, including neuroblastoma." (PMID 39317919, 2024). "This reduction leads to an increase in the secretion of CCL2 that recruits ionized calcium-binding adaptor molecule 1-expressing myeloid cells to enhance the proliferation of metastatic tumor cells in the brain." (PMID 38495881, 2024). "It is well known that MPE is associated with high levels of IL-6, CCL2, VEGF, TGF-β, and HIF, all of which are associated with maintaining a tumor phenotype resembling stem cells." (PMID 38549044, 2024). "TAMs themselves are recruited to premetastatic niches by a variety of tumor-secreted factors, such as CCL2, CSF-1, VEGF, PDGF, TNF-α, and TGF-β, where they act in a similar manner as in primary tumors, promoting cancer cell survival." (PMID 39516356, 2024). "Previous studies have shown that tumor-derived CCL2 and CCL5 can attract macrophages that enhance the metastatic capacity of the primary tumor (35, –37)." (PMID 39636862, 2024). "Macrophages also release RNS after infiltrating the tumor, resulting in nitration of CCL2 and thereby preventing CCL2-mediated recruitment of CTLs." (PMID 38254801, 2024). "CCL2 expression in the tumor microenvironment, involving various cell types, highlights its significance in cancer pathology and its potential as a therapeutic target." (PMID 39850880, 2024). "The CCL2/CCR2 chemokine axis is known to facilitate the migration of M-MDSCs to tumor sites, cultivating an immunosuppressive microenvironment." (PMID 38756774, 2024). "CCL2 is released by monocytes, tumor cells, and stromal cells in the TME, and its receptor, CCR2, plays an important role in the recruitment of bone marrow-derived monocytes into solid tumors and their development into TAMs." (PMID 39403370, 2024). "O2•−, in turn, plays a crucial role in enhancing the expression of C-C motif ligand 2 (CCL2), which serves to recruit macrophages and facilitate the development of the tumor microenvironment." (PMID 37469162, 2024).
tumor (continued). "Tumor cells can release the chemokine (C-C motif) ligand 2 (CCL2) upon activating IL-17RA signaling to attract macrophages into the tumor microenvironment." (PMID 39272855, 2024). "CCL-2 receptor (CCR2) expressing monocytes are recruited along a CCL2 gradient to the tumor periphery where they mature further in the TME and develop pro-tumoral functions." (PMID 39882242, 2024). "Within the tumor tissues, there was a greater presence of CCL2 and CCR2 in the stroma compared to the cancer nests." (PMID 39308672, 2024). "CCL2 is known as the predominant chemokine expressed by different tumor cells, and plays a pivotal role in the recruitment of immune cells, especially TAMs, through the CCL2/CCR2 axis." (PMID 38229160, 2024). "This, in turn, results in the production of CCL2, which promotes macrophage recruitment and reveals a new cross-talk between immune cells and tumor cells in the CRC microenvironment." (PMID 39090094, 2024). "In breast cancer, specific monoclonal antibodies can inhibit the recruitment of TAMs by inhibiting CCL2, thereby delaying tumor progression and metastasis." (PMID 39403370, 2024). "Intriguingly, we also observed a similar trend in CCL2 levels, both at the mRNA and protein levels, in tumor tissues, further confirming the positive correlation between PRPS2 and CCL2 in the LLC tumor tissues." (PMID 38952044, 2024). "It has also been shown that anti-folate receptor-α IgE reprograms and recruits macrophages in the tumor microenvironment to attack tumors via TNF-α/CCL2 signaling." (PMID 39596024, 2024). "Macrophages are recruited to tumor sites primarily through the CCL2/CCR2 axis and CSF-1/CSF-1R signaling, so blocking these two signaling axes also reduces macrophage infiltration." (PMID 38464516, 2024). "In tumor regions, the expression levels of CCL2, CCL5, CCL20, CXCL9, CXCL10, CXCL11 and CXCL12 were generally higher in hot tumors than in the other two groups." (PMID 37847338, 2024). "Cancer cells release various molecules, such as CC motif chemokine ligand 2 (CCL2), to recruit monocytes and macrophages to the primary tumor site, where they transform into TAMs3,4." (PMID 38355711, 2024). "It is widely accepted that TAMs originate from peripheral blood monocytes (PBMCs) and are recruited to the tumor vicinity by chemokines secreted within the tumor microenvironment, such as CCL2." (PMID 39206194, 2024). "In a KIAA1549::BRAF fusion-driven neural stem cells (NSC) model, CCL2 secreted by the tumor cells, and under the control of the MAPK pathway, was necessary for the recruitment of microglia cells promoting tumor formation." (PMID 38789691, 2024). "The interplay between UPP1high tumor cells and SPP1+ macrophages was linked with a variety of chemokines, including CCL2_CCR2, CCL3_CCR5, CXCL3_CXCR2, and CXCL8_CXCR1, as well as interactions such as IL1B_IL1_receptor and TGFB1_TGFbeta_receptor1." (PMID 38331898, 2024). "CCL2 is the primary chemokine expressed by tumour cells and plays a key role in attracting immune cells, particularly TAMs, via the CCL2/CCR2 axis." (PMID 38920685, 2024). "Cross-talk between tumor cells and TAMs is mediated by Ccl2/Ccr2 expression in the TIME, which is responsible for remodeling of the extracellular matrix, cancer progression, evasion of immunosurveillance, and angiogenesis." (PMID 38592450, 2024). "If the TME of PDAC contains numerous ligands that activate NK cells, such as CCL2, it can attract NK cells to infiltrate the tumor." (PMID 38590651, 2024). "CCL2 is known to be a strong promoter of monocyte and macrophage recruitment, which regulates the tumor immune microenvironment." (PMID 38970074, 2024). "Soluble pro‐inflammatory factors such as CCL2, CCL5, and CCL18 secreted by TAMs from the primary tumor have been implicated in the formation of a pre‐metastatic niche in distant organs such as the lungs and the bones, increasing tumor cell colonization." (PMID 38426622, 2024).
tumor (continued). "As expected, we also observed a similar trend in CCL2 levels, both at the mRNA and protein levels, in tumor tissues." (PMID 38952044, 2024). "These cells originate from circulating monocytes and tissue-resident macrophages that infiltrate tumor sites and undergo differentiation in response to multiple cytokines and growth factors (such as CCL2, CXCL4 and CSF-1)." (PMID 38409249, 2024). "An early study indicated that GP73 can upregulate chemokine C-C motif ligand 2 (CCL2) in tumor cells and facilitate its secretion." (PMID 39845976, 2024). "27-HC accumulates in tumor tissues and induces macrophages to secrete CCL2, CCL3, CCL4, and other chemokines to promote monocyte recruitment and differentiation to M2 type." (PMID 39596288, 2024). "Nevertheless, the presence of CCL2 in tumor patients leads to a detrimental impact on their prognosis, as it leads to the buildup of cell subtypes that suppress the immune system." (PMID 38970097, 2024). "Studies on the role of TLRs in NSCLCs show that activation of TLR-4 in NSCLC cells leads to increased regulation of pro-inflammatory cytokines and chemokines (TNF-α or CCL2), which contribute to the immunosuppressive nature of the tumor microenvironment." (PMID 39124797, 2024). "The CCL2 chemokine is a macrophage regulator that can also activate tumor cell growth and proliferation." (PMID 39769050, 2024). "Next, quantitative PCR was performed to evaluate the expression of the pro-tumour TAM-associated genes IL-10, CCL2 and IDO-1, which were all increased in both SKOV-3 and OVCA433 generated TAMs compared to pre-cultured autologous monocytes." (PMID 39763667, 2024). "This process is facilitated by bacterial translocation from the primary tumor site, which recruits neutrophils via cytokines such as IL-1β, CCL2, TNF-α, and IL-6, thereby establishing a pre-metastatic niche in the liver." (PMID 39795864, 2024). "CCL2 triggers the release of tumor-toxic granules in CD8+ T cells and NK cells, whereas MDSC-produced reactive nitrogen species can nitrify CCL2 (N-CCL2)." (PMID 39107856, 2024). "Activation of this pathway triggers the secretion of IL-6 by TAMs, which then enhances the levels of eukaryotic initiation factor 4A3 (EIF4A3) and the chemokine CCL2 in tumor cells." (PMID 39286635, 2024). "As such, solid cancer - BMN crosstalk not only impacts hematopoiesis but also tumor vascularization and even angiogenesis as CCL2 gradients recruit CCR2+ inflammatory Mos, which produces VEGF to increase vascular permeability." (PMID 39148724, 2024). "In particular, the HCC microenvironment is characterized by macrophages that are “programmed” by the tumor in an immunosuppressive way, due to the tumoral production of osteopontin and CCL2." (PMID 38791916, 2024). "Macrophage-induced mesenchymal-like tumor cells then secrete increased amounts of CCL2, which recruits macrophages, and IL-6, which leads to M2 polarization, further propagating EMT in a positive feedback loop." (PMID 39555068, 2024). "CCL2 polarizes macrophages toward the pre-tumor phenotype by binding to the surface of macrophages through the C-C chemokine receptor 2 (CCR2)." (PMID 38655133, 2024). "This study found that hypoxia‐induced miR‐210‐3p can limit the monocyte infiltration in lung tumors by modulating CCL2 expression, thus potentiating tumor progression in LUAD." (PMID 35658112, 2024). "The inhibition of CCL2 in MSC by CRISPR-Cas9 Knock out enhances MSC anti-tumor activity, with an increase in pro-inflammatory CD45+CD11b+ mononuclear myeloid cells in tumors." (PMID 39063032, 2024). "Consistent with our in vitro observations, mice implanted with PRPS2 knockdown cells exhibited a significant reduction in tumor volume and weight, concomitant with a decrease in CCL2 levels within the tumor tissues." (PMID 38952044, 2024). "MDSC recruitment to the tumor site is in part a response to glioma expression of chemokines CCL2 and CCL7, which are ligands of the CCR2 receptor expressed by MDSCs." (PMID 39307417, 2024).
tumor (continued). "CCL2 is the most potent chemoattractant in the tumor microenvironment, responsible for attracting macrophages and initiating inflammation." (PMID 38970097, 2024). "Dysbiosis in the breast microbiome can lead to inflammation in breast tissue, increasing M2-like macrophage infiltration, enhancing levels of interleukin (IL)-23, IL-22, CXCL-1, and CCL-2, and accelerating fibrosis within the tumor environment." (PMID 39717276, 2024). "Adding recombinant CCL2 and CSF1 proteins reversed the inhibition of macrophage M2 polarization, recruitment and tumor proliferation phenotypes caused by AS‐99 treatment." (PMID 39377228, 2024). "The majority of TAMs derive from circulating bone marrow (BM)-derived monocytes that migrate into the tumor bed mainly under the influence of chemokines (e.g. C-C motif ligand 2 (CCL2)), cytokine colony stimulating factor 1 (CSF-1), or complement components." (PMID 38426089, 2024). "Consistently, post-COJEC NB samples also revealed enhanced gene expression levels of CCL2 and a mesenchymal phenotype, consistent with the expansion of CCL2+ NB tumour cells." (PMID 37887559, 2023). "Along with this, higher expression of CCL2 correlated with higher engagement of TAMs, especially the M2 subtype to the tumor site, while blocking of the same impaired the M2 population recruitment." (PMID 38035101, 2023). "TAMs have a relatively short half-life and are therefore must be replaced continuously by inflammatory monocytes recruited from the bloodstream primarily in response to the chemokine CCL2, produced by tumor cells, tumor fibroblasts, and by myeloid cells." (PMID 37114134, 2023). "The average total tumour burden at 12 weeks of age was 1611.79 ± 154.57 mg for PyMT controls and 1695 ± 169.46 mg in PyMT/CCL2 mice." (PMID 37108548, 2023). "From these evidences, activation of multiple signalling pathways in inflammatory diseases, such as oxidative stress, infection, or tumour, ultimately leads to transcription factors transporting into the nucleus and enhancing the gene transcription of CCL2." (PMID 36872292, 2023). "Studies have confirmed that the CCL2-CC chemokine receptor 2 signaling pathway can be blocked by reducing the activation and proliferation of monocytes to promote tumor cell metastasis inhibition." (PMID 37251954, 2023). "We observe high levels of GM-CSF and CCL2 in lung tissue extracts from 4T1 tumor-bearing mice after radiotherapy and normal mice injected with exosomes, which showed a chemotactic tendency to M-MDSCs." (PMID 37268941, 2023). "We found that the CCL2 content was highest in nerves, which scored much higher when compared with acinus cells (P ˂ 0.0001), tumor cells (P ˂ 0.0001), immune cells (P ˂ 0.0001), and fibroblasts (P ˂ 0.001)." (PMID 37607005, 2023). "This is most likely due to the transient depletion of CCR2+ cells that reappear in peripheral blood shortly after ceasing the antibody treatment or tumor intrinsic adaptions alleviating the need for the CCR2/CCL2 axis." (PMID 37849753, 2023). "In a xenograft model, CCL2-induced inflammation dramatically increases tumor development and facilitates the establishment of a desmoplastic stroma in a xenograft model by early recruitment of macrophages and CAFs into the TME." (PMID 36880535, 2023). "Many tumors secrete large amounts of CCL2, thereby recruiting circulating inflammatory monocytes into tumor tissues where they then differentiate into M2 TAMs." (PMID 37114134, 2023). "The stiffness of the ECM supports the release of chemoattractants like CCL2 and colony-stimulating factor-1 (CSF-1) from CAFs and tumor cells." (PMID 36793444, 2023). "CCL2 was originally called a tumor-derived chemokine because it was discovered in tumor cells in vitro." (PMID 37445830, 2023). "In contrast to EC-Gαs-KO mice, EC-Gαs/Ccl2-dKO animals showed increased tumor cell proliferation, whereas tumor vasculature was hardly affected." (PMID 36374225, 2023).
tumor (continued). "FAP-positive CAFs are the major source of C–C motif chemokine ligand 2 (CCL2) which can promote tumor growth by enhancing the recruitment of myeloid-derived suppressor cells." (PMID 37316886, 2023). "The mean frequency of TAMs positive for CD14 or CD163 in the intratumoral stroma and CCL2+ tumor epithelial cells was higher in recurrences than in the corresponding primary tumors." (PMID 37208442, 2023). "We also infer that CCL2 expression remained high, supporting the possibility that this chemokine is a crucial mediator in recruiting monocytes to the tumor microenvironment." (PMID 37958292, 2023). "In vivo, irradiation also increased tumor cell expression of CCL2, which increased Treg recruitment into the TIME." (PMID 37377970, 2023). "The results of tumor tissue samples showed that the protein levels of chemokines CCL2 and CCL22, as well as TNF-α and IFN-γ, were significantly increased upon TCS treatment." (PMID 36674931, 2023). "CCL2 is a member of the chemokine family, which can promote tumor immune escape and cancer cell proliferation through recruitment of TAMs." (PMID 37889551, 2023). "It has been found that tumor cells express significant amounts of colony-stimulating factor 1, C-C pattern ligand 2 (CCL2), and monocyte chemotactic protein-1, something which contributes to TAMs’ function in tumor development." (PMID 37513975, 2023). "The expression of STAT3 in cancer-associated fibroblasts promotes the recruitment of myeloid-derived suppressor cells (MDSCs) in to the tumor by the production of C-C motif chemokine ligand 2 (CCL2) to create an immunosuppressive TME." (PMID 38273841, 2023). "The expression level of CCL2 mRNA was significantly higher in TGCTS0 tissues (n = 36) compared to benign tumors (n = 28) using qRT-PCR (P = .0024)." (PMID 37352031, 2023). "Pro-inflammatory M1 marker CCL2 decreases in tumour modules TH4 and PH4 but increases in the premalignant state." (PMID 38157373, 2023). "In contrast, tumor-derived soluble factors M-CSF, IL-6, IL-1β, IL-4, IL-10, CCL2 initiate the immunosuppressive pathways that commit immature myeloid cells to become MDSCs and further promote the differentiation towards M-MDSC." (PMID 38304256, 2023). "In a murine HCC study, incomplete RFA initially stimulated residual tumor cells to produce CCL2 through the upregulation of TNF-α, contributing to the infiltration and activation of TAMs." (PMID 36831664, 2023). "The MoDCs—derived in situ from tumor-infiltrating monocytes recruited by CSF-1 and CCL2—lack CCR7 expression and their anti-tumor activity would mostly entail an in situ activation of T-cell cytotoxicity in tumors." (PMID 37190135, 2023). "In tumor masses, microglia have native activity and can stimulate tumor growth by several cytokines and chemokines, such as IL-10, monocyte chemoattractant protein-1 (MCP-1/CCL2), some metalloproteinases (MMPs), and ARG1." (PMID 37170286, 2023). "By secreting CCL-2, IL-6, and CXCL8, FAP+ CAF-like cells are able to induce macrophages differentiation into tumor-associated macrophages." (PMID 37166418, 2023). "Collectively, these results suggest that Fn-Dps promotes tumor metastasis in vivo by CCL2/7-induced EMT." (PMID 36693067, 2023). "Coculture experiments demonstrated that these stromal cell responses were mediated by tumor-derived CCL2 and CCR2-mediated suppression of the T-cell activating cytokine CD154 (CD40L)." (PMID 37208442, 2023). "We found freshly sorted PDGFB tumor cells expressed higher levels of Ccl2, Ccl7, Ccl8, and Ccl12 relative to the same cells maintained in vitro (up to 6 passages) under both GSC and FBS conditions (P < 0.05)." (PMID 37733448, 2023). "YAP also promotes tumor progression by regulating tumor microenvironment, for example by promoting transcription of CCL2, a macrophage-specific chemokine, to recruit tumor-associated macrophages." (PMID 36123390, 2023).